RNU7-99P (RNA, U7 small nuclear 99 pseudogene)
Gene: Small nuclear RNA gene on chromosome 16 (6,748,908 to 6,748,969, forward strand). Ensembl gene ENSG00000252080.
Homologues: Orthologues: chimpanzee U7 (98% identical). Paralogues in human: RNU7-11P (85% identical), RNU7-14P (84% identical), RNU7-28P (84% identical), RNU7-8P (84% identical), RNU7-18P (82% identical), RNU7-21P (82% identical), RNU7-25P (82% identical), RNU7-3P (82% identical), RNU7-47P (82% identical), RNU7-4P (82% identical), RNU7-7P (82% identical), RNU7-128P (81% identical), and 142 more.